NAPRT (nicotinate phosphoribosyltransferase)
Diseases named in the same sentence as NAPRT in open-access papers (continued):
Sharing a sentence is not in itself a finding about the gene and the disease.
colon cancer (3 papers, 2019 to 2022). "We then revealed the genes that correlate with NAPRT/NAMPT expression in colon cancer and rectal cancer using UALCAN." (PMID 31448236, 2019). "There are 178 genes that significantly correlated with NAPRT expression in both colon cancer and rectal cancer." (PMID 31448236, 2019). "We found that promoter methylation of NAPRT gene is significantly decreased in colon cancer." (PMID 31448236, 2019).
gastric tumors (2 papers, 2021). "Since NAPRT is required to EMT inhibition through β-catenin, NAPRT suppression can promote EMT in gastric tumors." (PMID 33384409, 2021).
liver cancer (2 papers, 2022 to 2023). An epithelial or non-epithelial malignant neoplasm that arises from the liver. "Our results indicate that NAD biosynthesis is heterogeneous among liver cancer patients, and that Nicotinate phosphoribosyl transferase (NAPRT) levels are indicative of the NAD biosynthetic status." (PMID 36249025, 2022). "In vitro studies show that FK866 induces apoptosis of liver cancer cells (HepG2) via highly specific, non-competitive inhibition of nicotinamide phosphoribosyltransferase (NAPRT)." (PMID 36658296, 2023).
osteosarcoma (2 papers, 2017 to 2021). A usually aggressive malignant bone-forming mesenchymal neoplasm, predominantly affecting adolescents and young adults. "Therefore, low NAPRT expression could serve as a potential biomarker for the selection of osteosarcoma patients who could benefit from treatments that inhibit NAMPT." (PMID 34200964, 2021).
Alzheimer disease (1 paper, 2021). A progressive, neurodegenerative disease characterized by loss of function and death of nerve cells in several areas of the brain leading to loss of cognitive function such as memory and language. "RBP ZCCHC17, which has unique negative correlation with NAPRT expression, has been scarcely studied, but the most relevant studies place it as a regulator in Alzheimer’s disease." (PMID 34946971, 2021).
attention deficit-hyperactivity disorder (1 paper, 2021). A disorder characterized by a marked pattern of inattention and/or hyperactivity-impulsivity that is inconsistent with developmental level and clearly interferes with functioning in at least two settings (e.g. at home and at school). "Particularly in neural development, our results are supported by the established association of NAPRT mutations with neurological/neurodevelopmental diseases, namely, attention-deficit/hyperactivity disorder and schizophrenia." (PMID 34946971, 2021).
brain tumor (1 paper, 2017). "Here we have used 3C6D2 to detect NAPRT levels by IHC in multiple FFPE tumor tissue samples from patients with various lung and brain tumors." (PMID 29100430, 2017).
esophageal cancer (1 paper, 2022). A primary or metastatic malignant neoplasm involving the esophagus. "In recent years, the application of computer technology has identified chemical molecular formulas that are functionally similar to 2-HNa, promising the discovery of new NAPRT inhibitors for esophageal cancer therapy." (PMID 36432602, 2022). "Experiments in vitro found that NAPRT is overexpressed in esophageal cancer." (PMID 36432602, 2022). "The over-expression of NAPRT showed a significant positive correlation with the risk of EPL, which is consistent with our speculation based on studies related to esophageal cancer." (PMID 36432602, 2022). "More importantly, the significant over-expression of NAPRT in EPL patients may be related to the major pathway of NAD synthesis in esophageal cancer tissues." (PMID 36432602, 2022).
fibrosarcoma (1 paper, 2021). A malignant mesenchymal fibroblastic neoplasm affecting the soft tissue and bone. "GNE-617 showed robust antitumor activity in NAPRT-deficient xenograft mouse models, including prostate (PC3) cancer, fibrosarcoma (HT1080), and pancreatic (MiaPaCa-2) cancer, and resulted in more than 98% of the NAD reduction in tumors in vivo." (PMID 34068917, 2021).
lymph node metastasis (1 paper, 2019). "Our present study found that NAPRT and NAMPT were both highly expressed in CRC tissues, and correlate with vascular invasion, higher T-stage, lymph node metastasis and advanced TNM stage." (PMID 31448236, 2019).
melanoma (1 paper, 2017). A malignant, usually aggressive tumor composed of atypical, neoplastic melanocytes. "Interestingly, MALME-3M (melanoma) and H460 cells have strong expression of an apparent truncated NAPRT protein of approximately 35 kDa detected with 3C6D2 but not the HPA023739 polyclonal antibody." (PMID 29100430, 2017).
non-small cell lung carcinoma (1 paper, 2017). A group of at least three distinct histological types of lung cancer, including non-small cell squamous cell carcinoma, adenocarcinoma, and large cell carcinoma. "Among the remaining non-small cell lung cancer subtypes examined, 20-35 % of cases scored negative for NAPRT expression (0-10 % NAPRT positive) consistent with a previous report scored by IHC from paraffin embedded tissue using a different commercially available antibody." (PMID 29100430, 2017).
psoriasis (1 paper, 2021). An autoimmune condition characterized by red, well-delineated plaques with silvery scales that are usually on the extensor surfaces and scalp. "Preiss–Handler pathway seemed to show an intensified activity in psoriasis lesional skin, since up-regulation of the mRNA levels of genes encoding its components NAPRT, encoding nicotinate phosphoribosyltransferase, and NADSYN, encoding NAD synthetase, was observed." (PMID 34748530, 2021).
Sepsis (1 paper, 2019). Sepsis is defined as life-threatening organ dysfunction caused by a dysregulated host response to infection. "In line with our finding that NAPRT mediates endotoxin tolerance in vitro and in vivo, sera from patients with sepsis contain the highest levels of NAPRT, compared to patients with other chronic inflammatory conditions." (PMID 31511522, 2019). "Here we show that the intracellular NAD biosynthetic enzyme NAPRT is physiologically present at low levels in human sera and that its levels rise sharply in patients with sepsis or septic shock." (PMID 31511522, 2019).
triple-negative breast carcinoma (1 paper, 2018). An invasive breast carcinoma which is negative for expression of estrogen receptor (ER), progesterone receptor (PR), and human epidermal growth factor receptor 2 (HER2). "The triple-negative breast cancer model represented by MDA MB231 cells expresses NAPRT, an enzyme that was previously associated to resistance to FK866." (PMID 29541451, 2018). "Here, we investigated the molecular mechanism leading to acquired FK866 resistance in two genetically different cancer cell lines, CCRF-CEM T-ALL cells, which are NAPRT-deficient, and MDA MB231 triple-negative breast cancer cells, which, vice versa, express an active NAPRT enzyme but lack QPRT." (PMID 29541451, 2018). "The triple-negative breast cancer cell line, MDA MB231, was found to express NAPRT, to have low levels of QPRT, and to primarily rely on LDHA activity for its resistance to FK866." (PMID 29541451, 2018).
cancer (50 papers, 2014 to 2025). A tumor composed of atypical neoplastic, often pleomorphic cells that invade other tissues. "A novel NAMPT inhibitor (A4276) selectively targets NAPRT-deficient EMT subtype cancer cells and alleviates chemotherapy-induced peripheral neuropathy." (PMID 38469234, 2024). "This study aimed to identify a novel NAMPT inhibitor with enhanced selective cytotoxicity against NAPRT-deficient cancer cells as well as prominent efficacy in alleviating CIPN." (PMID 37771778, 2023). "Our approach involved selecting a derivative of a hit compound that likely targeted cancer cells with NAPRT deficiency as a biomarker." (PMID 37771778, 2023). "We confirmed that NAPRT deficiency can serve as an indicator of EMT-like cancers across various tumor types, underscoring the clinical significance of our compound." (PMID 37771778, 2023). "Overall, our study identified a novel compound, A4276, with great potential as a specific treatment for NAPRT-deficient EMT-like cancers." (PMID 37771778, 2023). "NAPRT deficiency serves as a biomarker for the response to A4276 as well as an indicator of EMT-subtype cancer in various tumor types." (PMID 37771778, 2023). "In this study, we developed and analyzed a novel NAMPT inhibitor, A4276, which exhibits remarkable anti-tumor activity against NAPRT-deficient EMT-subtype cancers." (PMID 37771778, 2023). "For example, in most EMT subtypes of gastric tumors, the loss of NAPRT expression makes cancer cells more dependent on NAMPT to produce NAD+." (PMID 35906622, 2022). "Due to their dependency on the Nam salvage pathway for survival, NAPRT-deficient cancers are extremely sensitive to treatment with NAMPT inhibitors." (PMID 35890155, 2022). "The loss of NAPRT activity makes cancer cells more vulnerable to the effect of NAMPRT inhibitors due to the total blockage of NAD+ production." (PMID 33384409, 2021). "Loss of NAPRT in cancer cells make cancer cells sensitive to NAMPT inhibitor FK866 and possibly also allow increasing the therapeutic efficiency of FK866 by coadministration of NA analog." (PMID 31448236, 2019). "It has been reported that promoter hypermethylation led to loss of NAPRT expression in most cancer types, with the frequencies ranging from 5 to 65%." (PMID 31448236, 2019). "Homozygous gene deletions of NAPRT are rare and loss of heterozygosity occurs in less than 20 % of cancer tissues according to The Cancer Genome Atlas (TCGA)." (PMID 29100430, 2017). "Recent studies have characterized NAPRT gene regulation and expression patterns including NAPRT splice variants in normal and cancer tissues." (PMID 29100430, 2017). "As a result, these NAPRT-deficient cancers are also particularly vulnerable to FK866." (PMID 38396769, 2024). "Consequently, it becomes imperative to identify effective NAMPT inhibitors that selectively target NAPRT-deficient cancers, both as monotherapy and in combination with standard chemotherapy, to overcome the challenges posed by potentially malignant tumors." (PMID 37771778, 2023). "In conclusion, the results strongly suggest that A4276 is an NAMPT inhibitor that exhibits remarkable selectivity against NAPRT-deficient EMT-like cancer cell lines across various cancer types while effectively sparing NAPRT-positive cells, particularly, normal cells." (PMID 37771778, 2023). "We hypothesized that A4276 has high selectivity for NAPRT-deficient cancer cells due to it inhibiting NAMPT enzymatic activity, as these cancer cells are likely dependent on NAMPT for NAD+ supply." (PMID 37771778, 2023). "Indeed, due to their dependency on the NAD+ salvage pathway, salvage-dependent cancers with NAPRT deficiency are sensitive to treatment with NAMPT inhibitors." (PMID 38116009, 2023).
cancer (continued). "NAPRT promoter hypermethylation in cancer is frequently associated with mutations in the protein phosphatase Mg2+/Mn2+-dependent 1D (PPM1D) or isocitrate dehydrogenase 1 (IDH1) genes, as well as with the epithelial-mesenchymal transition (EMT)-subtype of gastric cancer." (PMID 35890155, 2022). "We have previously studied NAPRT methylation and mutations in cancer." (PMID 34946971, 2021). "Indeed, NA supplementation was shown to rescue NAPRT-proficient cancer cell lines from NAMPTi-induced cytotoxicity, while it was unable to reverse NAMPTi-induced toxicity in NAPRT-deficient cells." (PMID 34068917, 2021). "In addition, NAPRT silencing in a BRCA2-deficient cancer cell line exacerbated DNA damage in response to chemotherapeutics." (PMID 29541451, 2018). "Interestingly, NAPRT-promoter hypermethylation in cancers could result from other specific mutations." (PMID 38396769, 2024). "Another first-generation NAMPT inhibitor, GMX1777, also displayed an improved therapeutic index against cancer cells with low NAPRT expression in vivo, when administered at high doses with nicotinic acid rescue." (PMID 40526635, 2025). "Accordingly, the rate-limiting enzyme of this NAD+ production pathway, NAPRT, has emerged as a promising target in cancer treatment." (PMID 38396769, 2024). "Given the emerging relevance of NAPRT inhibitors in cancer therapy, considerable efforts have been devoted to discovering more molecules that inhibit NAPRT." (PMID 38396769, 2024). "An extensive study that later explored NAMPT and NAPRT expression patterns across normal human tissues and cancer cell lines found that both NAMPT and NAPRT transcripts were widely expressed across normal human tissues." (PMID 38396769, 2024). "In line with this notion, elevated expression levels of NAPRT, the first enzyme in the PH pathway, were also found to occur in these two cancer types to support NAD+ biosynthesis." (PMID 38396769, 2024). "Given that the anti-tumor effect of NAMPT inhibitors can be reversed by NA supplemented in cell culture medium in NAPRT-dependent cancers." (PMID 38424218, 2024). "Cancers dependent on the NAD+ salvage pathway and deficient in NAPRT are sensitive to NAMPT inhibitors, while cancers dependent on the Preiss–Handler pathway with high NAPRT expression are resistant." (PMID 39272943, 2024). "According to the upregulated NAD+ synthesis pathway, cancer cells can be divided into PH-amplified tumors, many of which show NAPRT amplification, and salvage-dependent tumors, which are characterized by NAMPT enhancer remodeling." (PMID 38116009, 2023). "On the other hand, NAD+ supply of cancer that lack NAPRT expression is primarily dependent on NAMPT." (PMID 37175631, 2023). "A4276, an agent with greater selectivity than any other derivatives, was identified, and its selective cytotoxicity on NAPRT-depleted cancer cells was validated across multiple tumor types." (PMID 37771778, 2023). "It is worth mentioning that the inhibition of NAPRT decreases OXPHOS in cancer cells that overexpress NAPRT and makes them more sensitive to NAMPT inhibitors (NAMPTi)." (PMID 38116009, 2023). "As NAMPT and NAPRT are the rate-limiting enzymes of the two NAD+ biosynthetic pathways, neoplastic depletion of NAPRT can serve as a biomarker of NAMPT inhibitor-sensitive cancer." (PMID 37771778, 2023). "Taken together, these discoveries offer a rationale for focusing on NAMPT/NAPRT as an innovative approach to trigger metabolic impairment resulting in cancer cell death." (PMID 38116009, 2023). "Collectively, the structural data and NAMPT enzyme activity assays support the notion that A4276 confers a growth-inhibitory effect on cancer cells with decreased NAPRT levels by directly binding to and reversibly inhibiting the activity of NAMPT." (PMID 37771778, 2023).
cancer (continued). "The inverse correlation between the response to A4276 and NAPRT level was further validated through transcriptomic analysis of the cancer cell lines used, for which expression data were available in the DepMap dataset." (PMID 37771778, 2023). "To further confirm the observed sensitization effect of our putative inhibitors on the anti-tumor activity of NAMPT inhibitors, we extended our experiments in two additional NAPRT-expressing cancer cell lines (i.e., HCT116 and OVCAR-8)." (PMID 35890147, 2022). "Lowering specific NAD+ precursors in the diet, silencing or inhibiting NAPRT in cancer cells or depleting the gut microbiota using antibiotics are all potential avenues for optimizing the activity of NAMPT inhibitors in hematological malignancies." (PMID 35396381, 2022). "Due to the low potency of compound 1 on the human NAPRT enzyme (Ki equals 2.3 mM), in addition to its limited anti-cancer activity in our cancer cell models, we decided to exclude this compound from further experiments." (PMID 35890147, 2022). "We demonstrated that the NAPRT inhibitor 2-hydroxynicotinic acid (2-HNA) cooperates with the NAMPT inhibitor FK866 in killing NAPRT-proficient cancer cells that were otherwise insensitive to FK866 alone." (PMID 35890147, 2022). "NAPRT was found to be amplified in a large subset of solid human cancers such as ovarian, pancreatic, and breast cancers." (PMID 35890147, 2022). "NAMPT and NAPRT, as rate-limiting enzymes in these two pathways, play a crucial role in the occurrence and development of cancer." (PMID 35906622, 2022). "In the cited study, targeting NAPRT through silencing or chemical inhibition effectively sensitized NAPRT-expressing cancer cells to FK866 both in vitro and in vivo." (PMID 35890155, 2022). "Despite this emerging relevance of NAPRT as a potential target in cancer therapy, very few NAPRT inhibitors exist." (PMID 35890147, 2022). "Our best candidates, compound 8 and compound 19, were able to restore the sensitivity of NAPRT-expressing cancer cells to NAMPT inhibitors through NAPRT inhibition." (PMID 35890147, 2022). "Francesco and his colleagues performed a series of validation experiments that yielded several intriguing results: 1) Cancer cells overexpressing NAPRT were insensitive to FK866." (PMID 36160449, 2022). "We also demonstrated that NAPRT plays a central role in energy metabolism, DNA repair, and in protein synthesis in cancer cells via its ability to promote NAD production." (PMID 35890147, 2022). "A few studies have shown that NAPRT expression varies in different cancer types, making it imperative to assess NAPRT expression and functionality status prior to the application of therapeutic strategies targeting NAD." (PMID 34946971, 2021). "There is a controversy regarding the expression levels of NAPRT, the limiting enzyme of The Preiss–Handler pathway, in cancer." (PMID 33384409, 2021). "NAPRT activity inhibition and, consequently, the blockade of The Preiss Handler pathway force cancer cells to completely depend on the salvage pathway." (PMID 33384409, 2021). "In this context, NAPRT became an important biomarker for the use of nicotinic acid as a co-adjuvant in NAPRT-negative tumors and for co-inhibition in the cancer types that highly express NAPRT." (PMID 34946971, 2021). "On the other side, cancers displaying genetic alterations that suppress NAPRT activity are exquisitely vulnerable to NAMPT inhibitors’ monotherapy." (PMID 34068917, 2021). "Silencing of NAPRT in cancer cells reduces OXPHOS, protein synthesis, and ATP levels due to a reduction in mitochondrial NADH." (PMID 33609766, 2021). "Studies reported downregulation of the NAPRT gene in cancers such as glioblastoma and neuroblastoma." (PMID 33609766, 2021). "Differences in NAPRT expression between subtypes of cancer, namely in breast, pancreatic, lung and gastric carcinomas, suggest that individual variability should be considered in therapeutic approaches." (PMID 34946971, 2021).